FADD (Fas associated via death domain)
Diseases named in the same sentence as FADD in open-access papers (continued):
Sharing a sentence is not in itself a finding about the gene and the disease.
lung adenocarcinoma (12 papers, 2009 to 2025). A carcinoma that arises from the lung and is characterized by the presence of malignant glandular epithelial cells. "Related to this, increased levels of phosphorylated FADD have been linked to NF-κB hyperactivation in lung adenocarcinomas." (PMID 31569512, 2019). "This is in agreement with previous observations associating Ki67 and phospho-FADD in human lung adenocarcinoma and B-cell non-Hodgkin lymphoma." (PMID 27556297, 2016). "Increased expression of phosphorylated FADD causes cell cycle dysregulation, which may explain the low survival rate of lung adenocarcinoma patients." (PMID 37714937, 2023). "We then explored the effect of FADD on the malignancy of lung adenocarcinoma through in vitro experiments." (PMID 36936970, 2023). "For example, FADD overexpression and increased phosphorylation correlate with poor clinical outcome and reduced patient survival in human lung adenocarcinoma." (PMID 27556297, 2016). "In lung adenocarcinoma, FADD, a ferroptosis-related gene, was also identified as a predictor." (PMID 35664309, 2022). "Indeed, Fas-associated protein with death domain (FADD) is upregulated in lung adenocarcinomas, and expression of phosphorylated FADD correlated with poor clinical outcomes." (PMID 31937869, 2020). "However, how dysregulated FADD affects the development of lung adenocarcinoma (LUAD) remains unknown." (PMID 37671047, 2023). "Moreover, no mutations in FADD were found either in 92 samples from diverse hematological malignancies, in 24 lung adenocarcinomas with high FADD expression, in 15 osteosarcoma tumor samples, or in murine (14 samples) and human (22 samples) T-cell lymphoblastic lymphoma (T-LBL)." (PMID 31569512, 2019). "Nevertheless, increased FADD levels do not always coexist with FADD gene amplification, as reported in acute myelogenous leukemia or lung adenocarcinoma, suggesting the occurrence of additional mechanisms capable of modulating FADD levels in cancer." (PMID 31569512, 2019). "In vitro suppression of FADD reduced the proliferation of lung cancer cells and altered expression of apoptosis (BAX/BCL-2) and pyroptosis (Caspase-1/NLRP3) markers, suggesting that regulating pan-apoptotic markers may potentially become therapeutic targets for lung adenocarcinoma." (PMID 40831559, 2025).
autoimmune lymphoproliferative syndrome (11 papers, 2012 to 2025). Autoimmune lymphoproliferative syndrome (ALPS) is a rare, inherited disorder characterized by non-malignant lymphoproliferation, multilineage cytopenias, and a lifelong increased risk of Hodgkin's and non-Hodgkin's lymphoma. "Recently, using genome-wide linkage and whole exome sequencing, a homozygous missense mutation in the Fas-associated death domain protein (FADD) gene was found to be associated with autoimmune lymphoproliferative syndrome (ALPS)." (PMID 23231371, 2012). "Point mutations in the Fas death domain associated with autoimmune lymphoproliferative syndrome (ALPS) completely disrupted Fas reorganization and FADD recruitment, confirming structure-based predictions of the critical role that these residues play in Fas–Fas and Fas–FADD interactions." (PMID 35741037, 2022). "Recent studies have shown that the absence of RIPK3 along with either Caspase 8 or FADD caused a lymphoproliferative phenotype in B6 mice, similar to the lymphoproliferation found in Autoimmune Lymphoproliferative Syndrome." (PMID 27669412, 2016). "Autoimmune lymphoproliferative syndrome (ALPS) is due to autosomal dominant and somatic defects in the genes encoding FAS or FADD, leading to accumulation of activated T cells that have presumably escaped peripheral tolerance mechanisms." (PMID 40842819, 2025). "Autoimmune lymphoproliferative syndrome (ALPS), characterized by chronic lymphoproliferation, autoimmune manifestations, and an increased lymphoma risk, stems from defects in lymphocyte apoptosis, particularly in components of the apoptotic pathway (e.g., FAS, FASL, FADD, CASP10, and CASP8)." (PMID 38535602, 2024).
colitis (11 papers, 2016 to 2025). Inflammation of the colon. "Deficiencies in FADD or caspase-8 have been found to facilitate colitis development via MLKL-mediated necroptosis in epithelial cells." (PMID 38542202, 2024). "We found that DC-specific deletion of RIPK1 caused FADD-dependent spontaneous colonic inflammation characterized by increased neutrophil and Ly6C+ monocytes." (PMID 34462571, 2022). "Mice with IEC-specific FADD or caspase-8 deficiency develop colitis depending on MLKL-mediated epithelial cell necroptosis." (PMID 33050394, 2020). "In addition, loss of γδ T-IELs in FADD-DN mice aggravates DSS-induced colitis, suggesting that FADD is a relevant contribution to the field of mucosal immunology and intestinal homeostasis." (PMID 30250469, 2018). "Sensing of endogenous Z-DNA by ZBP1 has been shown to induce skin inflammation in mice with epidermis-specific RIPK1 knockout and colitis in mice with intestinal epithelial-specific FADD knockout." (PMID 41488643, 2025). "The ileal enteropathy associated with IEC knockout of NEMO, FADD, or CASP8 is TNFR1 independent, even though colitis in those mice is TNFR1 dependent." (PMID 35077396, 2022). "Collectively, these results indicate that DC-specific RIPK1 deletion confers the protection against DSS-induced colitis in a FADD-dependent but RIPK3-MLKL-independent manner." (PMID 34462571, 2022). "Compared with WT group, FADD-DN mice exhibited severe colitis with a distinct reduction in colon length." (PMID 30250469, 2018). "The decreased CD8α+TCRγδ+ T cells will take responsibility for the reduced homeostasis in intestinal mucosal immune system, so FADD-DN mice show more severe inflammation in DSS-induced colitis model." (PMID 30250469, 2018). "From day 3 to day 6 of DSS-induced colitis, a significant loss of body weight was observed in FADD-DN mice compared to WT mice, and the disease activity index (DAI) of FADD-DN mice also increased more dramatically." (PMID 30250469, 2018). "Loss of CD8+TCRγδ+ T means an impaired intestinal immunologic barrier, so FADD-DN mice develop more severe inflammation in DSS-induced colitis." (PMID 30250469, 2018). "In a model of spontaneous colitis using FADD-knockout mice, RIPK3 knockout prevented the development of spontaneous disease in the small intestine and colon." (PMID 29156831, 2017). "Mice with a conditional deletion of caspase-8 or FADD in the intestinal epithelium spontaneously undergo intestinal necroptosis and develop colitis." (PMID 29156831, 2017). "FADD is essential for maintaining intestinal homeostasis; mice that are deficient in FADD in the colon epithelium (FADDIEL-KO) develop spontaneous colitis." (PMID 27086921, 2016). "Moreover, mice with IEC-specific FADD deficiency (FADDIEC-KO) spontaneously developed epithelial cell necrosis with loss of Paneth cells and erosive colitis." (PMID 38542202, 2024). "Further investigation of FADD on mucosal immunology seems meaningful since the influence on CD8α+TCRγδ+ subset mediated by FADD might be involved in the initiation and/or perpetuation of colitis." (PMID 30250469, 2018). "The colitis in mice with conditional IEC knockout of NEMO, FADD, CASP8, and RIPK1 mice is largely reversed by TNF or TNFR1 deletion." (PMID 35077396, 2022). "The increased colonic inflammation and the resistance to colitis were restored by dual inactivation of RIPK3 and FADD, but not by inhibition of RIPK3, MLKL, or ZBP1 alone." (PMID 34462571, 2022).
non-small cell lung carcinoma (11 papers, 2010 to 2024). A group of at least three distinct histological types of lung cancer, including non-small cell squamous cell carcinoma, adenocarcinoma, and large cell carcinoma. "Decreased cellular FADD levels have been found in non-small cell lung cancer, and have been associated with FADD release into the extracellular space." (PMID 29051715, 2017). "SPOP has been reported to suppress tumorigenesis by inhibiting the NF-κB pathway in certain tumor types, indicating that this SPOP‒FADD‒NF-κB axis might represent a molecular mechanism underlying the role of FADD alteration in non-small-cell lung cancer." (PMID 31569512, 2019). "HS3ST1 has been found to promote tumor non-small-cell lung cancer progression by regulating SPOP/FADD/NF-κB pathway." (PMID 38173042, 2024). "Moreover, a decrease in FADD has been associated with poor clinical outcomes, such as drug resistance, inferior survival, increased recurrence or metastasis in many tumor types, such as human non-small cell lung cancer, thyroid adenoma/adenocarcinoma or acute myeloid leukemia." (PMID 36499482, 2022). "The release of FADD by non-small cell lung cancer cells is correlated with aggressiveness and metastasis." (PMID 36138066, 2022). "Although evidence from non-small-cell lung cancer (NSCLC) patients indicates that high FADD mRNA expression correlates with a poor survival prognosis, mechanistic insight into this correlation is lacking." (PMID 28212753, 2017). "In non-small cell lung cancer, the release of FADD may be involved in the metastasis of tumor cells." (PMID 37501725, 2023).
ovarian carcinoma (11 papers, 2014 to 2025). A malignant neoplasm originating from the surface ovarian epithelium. "IL-24 treatment is known to induce the expression of various members of the extrinsic apoptotic pathway, such as Fas cell surface receptor (Fas), Fas ligand (FasL), Fas-associated death domain (FADD) in human ovarian cancer cells, and death receptor 4 (DR4), in colorectal cancer cell lines." (PMID 30424508, 2018). "APG-1387 induced RIP1- and TNFα-dependent apoptotic cell death in ovarian cancer through downregulation of IAPs proteins and induction of caspase-8/FADD/RIP1 complex, which drives caspase-8 activation." (PMID 29530056, 2018). "Our results show that FADD levels are increased in the sera of women with ovarian cancer, with highest levels of FADD detected in late stage ovarian cancer." (PMID 29051715, 2017). "Further studies have revealed that SAL overcomes multidrug resistance in cisplatin-resistant ovarian cancer cells (A2780cis) by enhancing apoptosis through the upregulation of DR5 (death receptor-5), caspase-8, and FADD (Fas-associated protein with death domain)." (PMID 40507936, 2025). "Previous research reported that tea seeds saponins could also increase protein expression of DR5 and FADD and induced apoptosis in ovarian cancer cell, which are consistent with our results." (PMID 32752095, 2020). "Many of the same proteins that were identified by unsupervised hierarchical clustering and by linear regression analysis, were also significantly higher in the late stage ovarian cancer patients relative to the healthy women, e.g. MK, KLK6, hk11, CXCL13, FR-alpha, IL-6, and FADD." (PMID 29051715, 2017). "Three of these proteins, CXCL13, FADD, and TNFSF14 have not been reported in the literature as having an association with ovarian cancer, and may serve as novel candidate biomarkers for ovarian cancer." (PMID 29051715, 2017). "Notably, CXCL13, TNFSF14, and FADD had not been previously identified in ovarian cancer tissues or serum." (PMID 29051715, 2017). "By contrast, the knockdown of the adaptor protein FADD had a more modest effect, suggesting that FADD may provide some facilitating role in necroptosis in the ovarian cancer cells, yet was not critical in facilitating RIPK1 to RIPK3 signaling." (PMID 25356865, 2014).
colon carcinoma (9 papers, 2010 to 2022). "In colon cancer, curcumin induces FADD (Fas-Associated Protein With Death Domain), caspase-8, and caspase-3 and inhibits Wnt/beta-catenin signaling, triggering apoptosis." (PMID 36143462, 2022). "Moreover, somatic mutation in FADD and elevated expression of cFLIP has been attributed in the pathogenesis of colon carcinoma." (PMID 32961826, 2020). "Functional analysis revealed that HIF-1α inhibited the transcriptional activity of FADD gene in colon cancer cells by directly binding to HREs in its promoter." (PMID 36348274, 2022). "mTOR inhibitors suppress tumor cell growth and angiogenesis, and have recently been shown to induce death receptor/FADD-dependent apoptosis in colon cancers." (PMID 27351224, 2016). "Anti-proliferation and anti-angiogenesis activities of Rapalogs have been well-established, and our recent work demonstrated that activation of ER stress and the DR5/FADD-dependent apoptosis contributes significantly to their therapeutic response in colon cancer cells and xenografts." (PMID 27351224, 2016). "In addition to degrading ECM components, MMP’s were shown to confer apoptosis resistance by modulating Fas-FADD mediated death signaling and cleavage of Fas by MMP-2 resulted in decreased sensitivity of HT-29 colon carcinoma cells to Fas mediated apoptosis." (PMID 22962598, 2012).
glioblastoma (9 papers, 2010 to 2025). The most malignant astrocytic tumor (WHO grade IV). "Regarding the death receptor-mediated pathways, gene expression of several members of the TNF receptor family as well as FAS and FADD but also caspase-8 and caspase-7 was found to be reduced in human glioblastoma tissue." (PMID 34485282, 2021). "Other studies have also suggested that FADD is expressed in glial cells (e.g., glioblastoma cell lines;)." (PMID 28320441, 2017). "Taken together, these results showed that the co-expression of FasL and FADD synergistically enhanced apoptosis in primary human glioblastoma cells." (PMID 20942909, 2010). "However, even if the expression of TRAIL-R1 and TRAIL-R2 is increased in glioblastoma cells, resistance to TRAIL-induced apoptosis can be caused by low levels of caspase-8 and FADD." (PMID 34485282, 2021). "FADD was deficient in certain types of cancer, such as thymic lymphoma, acute myeloid leukemia (AML), and glioblastoma (GBM)." (PMID 36348274, 2022). "We found a consistent increase in Caspase 3/7 ratios across three distinct human glioblastoma neurosphere lines in response to FKBP38 knockdown, and this occurred in a mechanism dependent on FADD." (PMID 37947640, 2023). "Consequently, we reported an increase in the transcription and expression of the DISC complex components, including TNFR1, FADD and TRADD, leading to the activation of cleaved caspase 8 and ultimately resulting in caspase-dependent cell death of glioblastoma cells." (PMID 38212807, 2024). "It has been suggested that low levels of caspase-8 and FADD are related to apoptosis resistance via death inducers by TRAIL in glioma, since expression levels of the receptors TRAIL-R1 and TRAIL-R2 are increased in biopsy samples from astrocytoma and glioblastoma patients." (PMID 30486451, 2018).
head and neck squamous cell carcinoma (9 papers, 2016 to 2025). A squamous cell carcinoma that arises from any of the following anatomic sites: lip and oral cavity, nasal cavity, paranasal sinuses, pharynx, larynx, and salivary glands. "Fas-associated death domain (FADD) upregulation, i.e., gene amplification, protein phosphorylation and/or overexpression, has shown promising prognostic implications in head and neck squamous cell carcinoma (HNSCC)." (PMID 32847023, 2020). "In head and neck squamous cell carcinoma, FADD, DR5 and caspase-8 have been reported to be associated with tumor growth and metastasis." (PMID 27286445, 2016). "In recent studies, FADD has been used as a potential autophagy-related prognostic marker in lung squamous cell carcinoma and head and neck squamous cell carcinoma." (PMID 34336650, 2021).
pancreatic cancer (8 papers, 2003 to 2024). "For example, FADD has been reported to protect pancreatic cancer cells from anticancer drug-induced cell death." (PMID 32194778, 2020). "It was reported that p21-activated protein kinase 1 induced the invasion of gastric cancer cells through c-Jun NH2-terminal kinase-mediated activation of matrix metalloproteinase-2, and FADD protected pancreatic cancer cells from drug-induced apoptosis." (PMID 28713815, 2017). "This in conjunction with reduced FADD expression clearly contributes to the acquired apoptosis resistance of pancreatic tumour cells." (PMID 14583775, 2003). "In conclusion, PW06 can potent binding ability to the Fas-FADD which led to antiproliferative, cytotoxic activities, and apoptosis induction accompanied by the caspase-dependent and mitochondria-dependent pathways in human pancreatic cancer MIA PaCa-2 cells." (PMID 36820406, 2023). "Thus, the apoptosis pathway assumes that PW06 interacted with the Fas-FADD proteins and then activates the caspase-independent apoptotic pathway (mitochondria-related pathway) and the caspase-dependent apoptotic pathway in human pancreatic cancer MIA PaCa-2 cells." (PMID 36820406, 2023). "While FADD has recently been reported to have a protective role against anticancer drug-induced cell death in pancreatic cancer cells 9, there are no reports on the effect of FADD knockdown on cell death in OS induced by death ligands such as TNFα or TRAIL." (PMID 32194778, 2020).
acute myeloid leukemia (7 papers, 2005 to 2022). Acute myeloid leukemia (AML) is a group of neoplasms arising from precursor cells committed to the myeloid cell-line differentiation. "In cancers, including acute myeloid leukemia, the apoptotic pathway is frequently inhibited by upregulating antiapoptotic proteins or downregulating caspase-8 and FADD." (PMID 34663800, 2021). "A study on acute myeloid leukaemia reported that reduced FADD in leukaemic cells at diagnosis indicated bad prognosis." (PMID 27556297, 2016). "Similarly, in 57 patients with acute myeloid leukemia (AML), we observed that FADD expression was significantly lower in the group of patients that did not survive after 3 years." (PMID 36499482, 2022). "We looked for FADD protein expression in human acute myeloid leukemia (AML) cells." (PMID 15717929, 2005). "For example, it was demonstrated that transcription was not altered in samples from acute myelogenous leukemia exhibiting reduced FADD protein." (PMID 31569512, 2019).
head and neck cancer (7 papers, 2014 to 2019). A primary or metastatic malignant neoplasm affecting the head and neck. "The Fas Associated Death Domain (FADD), a protein involved in apoptotic signaling, along with additional roles in cell proliferation, has been associated with nodal metastasis, overall and disease-free survival in patients with head and neck cancers." (PMID 26808319, 2016). "It was reported that high levels of Fas/DR5/FADD/caspase-8 death signaling play a critical role in regulation of cancer metastasis in human head and neck cancer." (PMID 27286445, 2016). "It has been reported that Fas/DR5/FADD/caspase-8 death signaling pathway plays a critical role in regulation of cancer metastasis in human head and neck cancer." (PMID 27286445, 2016). "A significant number of genes were amplified in greater than 30 percent of cancer patients, including DCUN1D1 (43% of lung squamous cancers), FADD and PPFIA1 (∼30% of head and neck cancers), and PRKCI (36% of lung squamous cancers)." (PMID 24874471, 2014). "In tumor types with frequent FADD amplification, such as head and neck cancer, it has been suggested that combined treatment with SMAC mimetics (Birinapant) and radiation may be particularly useful as FADD is key in sensitization to cell death." (PMID 31569512, 2019).